KLRG1 (killer cell lectin like receptor G1)
Diseases named in the same sentence as KLRG1 in open-access papers (continued):
Sharing a sentence is not in itself a finding about the gene and the disease.
tumor (continued). "This indicated that KLRG1 may influence the proliferation of tumor cells through the biding of E-cadherin." (PMID 34187403, 2021). "And we are the first study to focus on the direct role of KLRG1 on tumor cells." (PMID 34187403, 2021). "The tumor promotion effect was eliminated in KLRG1 knockdown A549 cells." (PMID 34187403, 2021). "Tumor-bearing scaffolds had lower expression of interferon γ (Ifng) and killer cell lectin like receptor G1 (Klrg1), markers of T-cell activation/effector T cells, and, conversely, up-regulation of coagulation factor II thrombin receptor (F2r), a marker of exhausted T cells." (PMID 33782087, 2021). "Since KLRG1+ NK cells are important for tumor cell killing in vivo, we asked whether αGC treatment also enhanced the functional capacity of this subset." (PMID 33467442, 2021). "So, we need sensitive methods, such as PCR, to detect the expression of KLRG1 in tumor tissues." (PMID 34187403, 2021). "As KLRG1 was abundantly expressed on the surface of T cells and NK cells, we speculated that the expression of KLRG1 on tumor cells would competitively bind E-cadherin in tumor microenvironment which would promote the activity of T cells and NK cells." (PMID 34187403, 2021). "Knockdown of KLRG1 promoted the proliferation of A549 and H1299 tumor cells." (PMID 34187403, 2021). "Furthermore, blocking the ATM-dependent DNA damage response pathway during NK cell activation led to enhanced NK cell activity, downregulation of KLRG1, improved persistence, and better tumor clearance in a murine B cell lymphoma model." (PMID 33120910, 2020). "Klrg1 is expressed by the majority of tumor-specific T cells in the spleens of tumor-bearing mice." (PMID 33584701, 2020). "We speculated that besides the relatively low E:T ratio in large tumor burdens, antitumor effects of KLRG1+CD8 T cells would also be repressed because of the interaction of their inhibitory molecules and the rapidly deteriorating tumor microenvironments." (PMID 31664180, 2019). "We studied KLRG1 expression in human blood and tumor samples from available genomic datasets." (PMID 30858925, 2019). "Functional evaluation demonstrated that these KLRG1+CD8 T cells could kill tumor cells in vitro and in vivo in Granzyme B- and Fas/FasL-dependent manners with no tumor antigen specificity, and tend to migrate into tumor sites by high expression of heparanase." (PMID 31664180, 2019). "Thus, increased ability of individual KLRG1+ NK cells to mediate tumor killing cannot account for impaired metastasis development in Ackr2−/− mice." (PMID 30158126, 2018). "Indeed, analysis of the relative proximity of dye-labeled, adoptively transferred, KLRG1+ NK cells from WT and Ackr2−/− mice to tumor deposits indicated that NK cells from Ackr2−/− mice migrated closer to CCL2-expressing tumors than WT cells." (PMID 30158126, 2018). "Moreover, a key finding from our study demonstrated that the increase of tumor-infiltrating Ag-specific CD8+ T cells with KLRG1+ effector phenotype can play a role in eliciting tumor clearance in the combination Vax/aGITR/aPD-1 therapy." (PMID 28388572, 2017). "In tumor microenvironment, KLRG1 is significantly overexpressed in T cells." (PMID 29237456, 2017). "TGF-β-deficient CD8+ T cells exhibited higher KLRG1 expression in vivo, suggesting that TGF-β may promote CTL-mediated tumor rejection through reciprocal regulation of KLRG1 and CD103." (PMID 27314056, 2016). "However, the roles of KLRG1 on human T cells especially in tumor microenvironment have not been fully understood." (PMID 27557510, 2016). "However, the expression and role of KLRG1 on human T cells in the tumor microenvironment remain to be well addressed." (PMID 27557510, 2016). "Our results indicated KLRG1 might contribute to the impaired antitumor immunity of memory T cells in tumor microenvironment." (PMID 27557510, 2016). "Our results showed KLRG1 expression on T cells significantly increased in tumor microenvironment." (PMID 27557510, 2016).
tumor (continued). "The roles of human KLRG1+ Treg cells in tumor microenvironment deserve to be further investigated." (PMID 27557510, 2016). "Tumor cells have developed specific mechanisms to induce tolerance, inhibition, and exhaustion of immune effector cells, by altering the expression of PD-1 and KLRG1 on T cells." (PMID 24884733, 2014). "Mechanistic studies revealed that dual anti-OX40/IL-2c therapy significantly increased the proliferation (Ki-67) and differentiation (granzyme B) of anergic tumor-associated Ag-specific CD8 T cells, while reducing their expression of the senescence-associated molecule KLRG1." (PMID 22496812, 2012). "In addition, we identify KLRG1 as a useful marker for monitoring the anti-tumor immune response elicited by this therapy." (PMID 21559358, 2011). "Furthermore, KLRG1 may mark circulating cytotoxic CD4+ T cells with tumor-matched TCRs to allow their isolation, which we validate below." (PMID 40299576, 2025). "Moreover, KLRG1 can also cause functional depletion of NK cells by binding to soluble N-cad released by circulating tumor cells in a noncontact cell‒cell manner." (PMID 38898461, 2024). "Additionally, we discuss the potential applications of KLRG1 as a tool for tumor immunotherapy." (PMID 38898461, 2024). "KLRG1 has demonstrated significant antitumor and inhibitory effects on tumor growth in a wide range of malignant tumors, while KLRG1-targeted inhibitors have also been developed as tumor immunotherapies and have been a popular area of research in immunotherapy." (PMID 38898461, 2024). "CTLA-4, TIGIT and KLRG1 may thus contribute to the reduced anti-tumor activity in aging mice." (PMID 37752597, 2023). "Additionally, combined blockade of KLRG1 with PD-1 can promote NK and T cell anti-tumor immunity." (PMID 35265614, 2022). "Importantly, in several mouse tumor models, it was found that KLRG1 checkpoint blockade resulted in heightened anti-tumor immunity and better outcomes, while KLRG1/PD-1 combination therapy resulted in reduced primary tumor growth as well as metastasis development." (PMID 35572605, 2022). "So, KLRG1 may also play a directly role to the tumor differentiation and progression." (PMID 34187403, 2021). "Here, we point out the distinct anti-correlation of KLRG1 expression with PD-1 and other checkpoint receptors in human CD8 T cell tumor infiltrating lymphocytes (TILS)." (PMID 39832302, 2025). "The high expression of inhibitory receptors such as LAG3,KLRG1, and TIM3 implies that the abnormal expression of these molecules is closely related to T-cell functional failure and the weakening of anti-tumor immune responses." (PMID 41394809, 2025). "Taken together, this analysis shows a mixed phenotype, as potentially tumor-induced immunosuppressive molecule such as CD73 is upregulated in peripheral T cells, whereas others, such as TIGIT and KLRG1, are reduced in NSCLC BM patients." (PMID 40346687, 2025). "The results demonstrated that the expression levels of KLRG1 and ST2 in ILC2s derived from tumor tissue were comparatively lower when compared to ILC2s derived from splenic tissue." (PMID 38430390, 2024). "Collectively, these findings suggest that while the abundance of ILC2s in tumor tissues is higher, a majority of these cells exist in a quiescent state characterized by diminished expression levels of ST2 and KLRG1." (PMID 38430390, 2024). "In vivo, the combination therapy induced more proliferative KLRG1‐high PD1‐low CD8+ T‐cells and activated CD103+ DC in the tumor site and increased tumor‐specific CD44+ CD8+ T‐cells in the lymph node." (PMID 38400597, 2024). "This dual modulatory effect was mirrored in tumor-infiltrating NKT cells, where a decrease in the percentage of PD-1+, FoxP3+, IL-10+, and KLRG1 MFI+ expression was accompanied by an upregulated expression of the activating receptors NKp46 and FasL." (PMID 38892058, 2024).
tumor (continued). "In tumor-bearing mice treated with rmIL-33 and anti-PD-1, ILC2s exhibited distinct phenotypic alterations, characterized by heightened expression of ST2 and KLRG1." (PMID 38430390, 2024). "KLRG1 blockade works synergistically with PD-1 checkpoint therapy, which increases the frequency and maturation of CD8+ T-cells and NK cells in the tumor microenvironment, promoting antitumor immunity against melanoma tumor growth." (PMID 38898461, 2024). "We found that in the tumor tissues of tumor-bearing mice, nILC2s (ST+KLRG1− ILC2s), iILC2s (ST2−KLRG1+ ILC2s), and mILC2s (ST2+KLRG1+ ILC2s) were almost undetectable and most of the ILC2s were in a quiescent state." (PMID 38430390, 2024). "On day 9 after tumor inoculation, we observed reduced expression of CTLA-4, KLRG1 and ICOS in Il23r-KO Treg cells." (PMID 38356059, 2024). "We noticed that the presence of CD127+/KLRG1+ CD8 T cells was positively correlated with that of CD20+ B cells and CD4+ T cells in both post-NAC and post-NAPC tumor tissues, indicating a possible intercellular interaction between these cell types." (PMID 37231145, 2023). "In untreated and PDOX-treated mice, the majority of tumor-infiltrated CD8+ T cells expressed CD431B11, NKG2A, and/or KLRG1." (PMID 36796366, 2023). "Even though Lenti‐HPV‐07 treatment led to complete tumor eradication, there was an increase in the frequency of intra‐tumoral CD44dim CD69− KLRG1+ exhausted T cells, which most likely resulted from continuous checkpoint signaling and antigenic stimulation." (PMID 37675835, 2023). "Both CD38 and KLRG1 expression on T cells are increased in the TME and up-regulated in human tumor samples after therapies, potentially contributing to adaptive resistance." (PMID 37207205, 2023). "Here, we show that the spleen is a critical site harboring tumor-specific CD8 T cells that functionally segregate based on differential Cxcr3 and Klrg1 expression." (PMID 36472588, 2023). "Of significance, the expression of coinhibitory receptors (PD1, KLRG1, LAG3, and TIM3) was considerably lower in CD8+ T cells retrieved from B16 Mgst1 KD tumor, and there was an increase in cytokine response (IFNγ and TNFα) along with Granzyme B." (PMID 37321450, 2023). "The absolute number of effectors PD-1+ CD8 T cells, defined as SLECs (KLRG-1+ / IL7Rα-) and MPECs (KLRG-1- / IL-7Rα+) were significantly augmented in tumor infiltrates of HVEM KO tumors compared to that of HVEM WT tumors." (PMID 37033927, 2023). "In MethA tumor-bearing mice, metformin treatment decreased tumor-infiltrated Treg cells, especially terminally differentiated CD103+ KLRG-1+ Treg cells (active effector Treg cells) accompanied with a decrease in the inhibitory molecules expressed on them." (PMID 37686159, 2023). "KLRG1+ CD8+ T cells were markedly increased by mJX-594 treatment and further increased by anti-PD-1 combination treatment in both the tumor and spleen." (PMID 35453555, 2022). "αPD-L1 expanded tumor-specific T cells in the spleen whereas αCD40 reduced intratumoral regulatory cytokines, reduced TEX, and promoted Klrg1+ cytotoxic intratumoral T cells." (PMID 35393950, 2022). "Moreover, serum sE-CAD/KLRG1 axis may inhibit KLRG1+ cytotoxic T-cells and NK cells function in the peripheral blood, probably suppressing their cytokine secretion and proliferation both in the periphery and in the tumor microenvironment." (PMID 35267574, 2022). "In our current study, we found a positive correlation between KLRG1 and the infiltration of different antigen-presenting cells, revealing that KLRG1 could induce tumor immunity and immune memory, and could be used as a potential tumor antigen for mRNA vaccines." (PMID 35265614, 2022). "Tumor-free survival required IFNγ-dependent expansion of CD8+ T cells and was related to 4-1BB-mediated differentiation of KLRG1+ effector CD8+ T cells." (PMID 34267616, 2021).
tumor (continued). "Future studies should delineate the function of KLRG1 on ILC2-derived cytokine production, proliferation and implications for anti-tumor immunity." (PMID 34885076, 2021). "Similar to infection settings, OT-1 T cells overexpressing PGC-1α showed the phenotypic hallmarks of memory T cells, as illustrated by a higher percentage of KLRG1− CD127+ cells in the periphery and at the tumor site compared to SCR." (PMID 32055005, 2021). "Despite the increase in KLRG1+ CD8+ T-cells, similar tumor responses were observed between CVA21-treated naïve or immunized cohorts." (PMID 34503272, 2021). "The results showed that knockdown of KLRG1 also reduced the expression of BTK and CCR2 in A549 tumor cells." (PMID 34187403, 2021). "In terms of anti-tumor immunity, EZH2+CD8+ T cells are often void of dysfunction markers (KLRG1, Tim-3, CD57), and the EZH2+CD8+ T cell population positively correlates to anti-tumor response." (PMID 35087832, 2021). "Most of TEX cells were likely tumor-reactive T cells because of high levels of CD39 (ENTPD1) and CD103 (ITGAE) and very low level of KLRG1 38–41." (PMID 34489433, 2021). "We found that TOX and potentially TIM-3, CTLA-4, VISTA, TIGIT, KLRG1, TOX2, SIRT1, Ki-67, and Helios mRNA levels in tumor tissue were elevated in advanced disease stages, suggesting their potential roles in CRC progression." (PMID 32393998, 2020). "Together, these data suggest that TOX, and potentially TIM-3, CTLA-4, VISTA, TIGIT, KLRG1, TOX2, SIRT1, Ki-67, and Helios mRNA levels in CRC tumor tissues increase in advanced disease stages, suggesting their possible roles in CRC progression." (PMID 32393998, 2020). "Tumor infiltrating innate lymphoid cells (ILCs) can show an activated phenotype (expression of CD69, CD44, MHCII, and KLRG1) and provide tumor immunosurveillance." (PMID 33266109, 2020). "Therefore, compared with KLRG1−CD8 T cells, higher expression of heparanase might contribute to the migration of KLRG1+CD8 T cells into tumor sites, where KLRG1+CD8 T cells could exert stronger cytotoxicity against tumor cells in FasL- and Granzyme B-dependent manners." (PMID 31664180, 2019). "Besides, the expression of cytotoxicity-associated molecules, including granzyme, perforin, Fas/Fas Ligand and TRAIL, was higher in KLRG1+CD8 T cells than in KLRG1−CD8 T cells, suggesting that KLRG1+CD8 T cells might have higher cytotoxicity against tumor cells." (PMID 31664180, 2019). "Tumour infiltrating ILC were found to show an activated phenotype with higher expression of MHC-II, KLRG1, early activation marker CD69 and CD44." (PMID 29587679, 2018). "We propose that T cells chronically driven by tumor antigen eventually lose expression of CD127 and KLRG1 becoming terminally differentiated." (PMID 30327458, 2018). "This leads to increased recruitment of KLRG1+ NK cells to CCL2-expressing tumors and enhanced tumor killing." (PMID 30158126, 2018). "In a mouse model of B cell lymphoma, treatment with α-GalCer-loaded, irradiated tumor cells and α-4-1BB increases overall survival and tumor-free survival dependent on IFN-γ and KLRG1+ CTLs." (PMID 29163518, 2017). "More CAL-101 donor cells expressed a central memory phenotype within the tumor, however, the percentage of PD1+ and KLRG1+ donor cells were similar between groups." (PMID 29033940, 2017). "Thus, we hypothesized that declined miR-101 expression in human KLRG1+ T cells leaded to elevated expression of co-repressor CtBP2, which subsequently suppressed the effector cytokine production of KLRG1+ T cells, resulting in impaired T cell antitumor immunity in tumor microenvironment." (PMID 27557510, 2016). "Therefore, our work suggested that repressing KLRG1 could be a novel therapeutics against tumor." (PMID 27557510, 2016).
tumor (continued). "On the basis of the findings regarding the chemokine receptor CX3CR1, two killer lectin-like receptor G1 (KLRG1+) mouse NK cell subsets have been defined, and KLRG1+CX3CR1+ NK cells have been found to display impaired IFN-γ production and tumor cell lysis." (PMID 26655673, 2015). "Distinct from other co-stimulatory antibodies, we found that α4-1BB induced striking upregulation of KLRG1 on CD8+, and to a lesser degree CD4+, effector T-cells in the tumor." (PMID 21559358, 2011). "On tumor infiltrating CD8+ T-cells, there was a striking upregulation of PD-1 and of the surface receptor KLRG1 in response to both α4-1BB and combination antibody treatment." (PMID 21559358, 2011). "The persistence of markers such as GLUT1, CD57, PD-1, KLRG1, and soluble TIM-3/Gal-9, along with altered protease profiles, suggests a chronic immunosuppressive microenvironment that may impair tumor surveillance and immune resilience." (PMID 41208973, 2025). "Additionally, we have also obtained single-cell TCRαβ sequences from expanded KLRG1+ and KLRG1– CD4+ T cells from PBMCs, and matched total CD4+ T cells from tumor, of 2 patients." (PMID 40299576, 2025). "The high frequency of KLRG1 expression is noteworthy, as it was found in approximately 80% of cytotoxic CD4+ T cells, identifying this as a surface marker allowing isolation of this population and its enriched repertoire of tumor-shared clones." (PMID 40299576, 2025). "In a separate patient, we confirmed enhancement of tumor killing by circulating and intratumoral CD4+ T cells by E-cadherin blockade that is specific for KLRG1, and also MHC class II in agreement with our prior findings, and was not impacted by isotype control antibodies." (PMID 40299576, 2025). "While KLRG1–CD4+ T cells have some spontaneous killing activity due to the presence of tumor-specific T cells that are not inhibited by KLRG1, E-cadherin blockade did not enhance their killing." (PMID 40299576, 2025). "For the first tumor, neither KLRG1– nor KLRG1+ CD4+ T cells from PBMCs increased tumor cell death when coincubated without treatment." (PMID 40299576, 2025). "Genes such as BCL7A and GRB10 may exert anti-cancer effects by promoting immune cell infiltration, whereas KLRG1, THEM4, and TDRD9 might suppress immune cell infiltration, facilitating tumor progression." (PMID 39867577, 2024). "Short-term effector cells (TE; KLRG1+ CD127−) and memory precursor cells (MP; KLRG1− CD127+) are distinguishable, with TEs perishing within days to weeks, while MPs evolve into TMEMs and provide prolonged protective tumor immune responses." (PMID 39538305, 2024). "For example, overexpression of GRB10 and TDRD9 may enhance cancer cell proliferation, while downregulation of BCL7A, GPR18, KLRG1, and THEM4 could contribute to reduced immune surveillance and tumor evasion." (PMID 39867577, 2024). "However, Foxp3UP CD8 T cell in the tumor exhibited a more activated and differentiated phenotype with higher expression of CD43 (130-kD), CD69, CD39, and KLRG1." (PMID 36045586, 2023). "We first examined KLRG1 expression in T cells of WT and Mlkl KO MMTV-PyMT mice and found that the population of KLRG1 expressing T cells in tumor-infiltrating and spleen T cells are not affected by MLKL deletion." (PMID 36703228, 2023). "On the other hand, metformin combination with C-REV does not decrease terminally differentiated CD103+ KLRG-1+ T regulatory cells in both the injected and contralateral tumor sides compared to the single-treated groups in bilateral Pan02 tumor model." (PMID 37686159, 2023). "Moreover, previous studies have reported that IL15 superagonist-stimulated NK cells enhance in vivo antitumor efficacy by promoting tumor infiltration, and IL15-expanded KLRG1+ NK cells protect mice from pulmonary metastatic colorectal carcinoma." (PMID 37570749, 2023).